ANXA1 (annexin A1)
Diseases named in the same sentence as ANXA1 in open-access papers (continued):
Sharing a sentence is not in itself a finding about the gene and the disease.
breast carcinoma (continued). "Furthermore, we also evaluated the changes of ECM1 and ANXA1 levels in the uEVs from breast cancer patients before and after surgery using CLIA." (PMID 39040439, 2024). "In addition, the protein levels of ECM1 and ANXA1 in the uEVs of MMTV-PyMT transgenic mice were observed to increase progressively with the progression of breast cancer." (PMID 39040439, 2024). "For example, within TME, increased activation of retinoic acid (RA) can drive intra-tumoral monocytes differentiated toward TAMs but shift away from differentiating into DCs via suppression of IRF449; ANXA1 promotes alternative macrophage polarization to enhance breast cancer growth." (PMID 38645221, 2024). "This suggests that ECM1 and ANXA1 in uEVs could be potential biomarkers for early diagnosis of breast cancer." (PMID 39040439, 2024). "We hypothesized that NTF4 combined with ANXA1 may be combined predictive and therapeutic targets for breast cancer." (PMID 36632451, 2023). "The expression of ANXA1, is influenced by various factors in breast cancer." (PMID 37507468, 2023). "Moreover, ANXA1 nuclear translocation promotes expression of the pro-apoptotic Bid gene, which activates the caspase-3 apoptosis cascade, ultimately resulting in breast cancer cell apoptosis." (PMID 36632451, 2023). "Moreover, inhibition of PRKDC/AKT signaling and ANXA1 effectively rescues NTF4-mediated breast cancer metastasis and invasion." (PMID 36632451, 2023). "Moreover, studies have reported that Annexin A1 (ANXA1) enhances metastatic activity of breast cancer cells by promoting EMT 32-34." (PMID 36632451, 2023). "In addition, Vecchi has reported that inhibiting AnxA1/FPR1 autocrine axis can reduce breast cancer cell growth and aggressiveness both in vitro and in vivo." (PMID 35928443, 2022). "Moreover, a tissue microarray analysis described that decreased expression of ANXA1 is correlated with breast cancer development and progression." (PMID 35631574, 2022). "Based on our current results and our previous findings that ANXA1 is involved in breast cancer growth, we hypothesized that ANXA1 may also play a role in stress-induced tumor development." (PMID 35664067, 2022). "Overexpression of ANXA1 promotes metastasis in breast cancer patients, resulting in poor prognosis." (PMID 35711921, 2022). "In this study, we hypothesized that ANXA1 is involved in stress-related promotion of breast cancer development and determined its role in the regulation of microbiome, gut-serum metabolites." (PMID 35664067, 2022). "Inhibition of ANXA1 and/or its receptor may be therapeutically rewarding in the treatment of breast cancer and secondary metastasis to the brain." (PMID 35382852, 2022). "ANXA1 has been extensively studied in gastric cancer and breast cancer." (PMID 35711921, 2022). "Finally, the overall expression level changes in ANXA1 in the various subtypes of breast cancer and brain cancer using was determined using TCGA." (PMID 35382852, 2022). "ANXA1 has been suggested as a biomarker in cholangiocarcinoma and several other cancers including colorectal, lung, liver, pancreatic and breast cancers, all of which are extremely heterogeneous and require good biomarkers to inform treatment decisions." (PMID 35146757, 2022). "Furthermore, TNBC is a heterogenous breast cancer that can be subclassified into six subtypes, but most of the mechanistic studies on AnxA1 covered only the mesenchymal, BL1 and BL2 TNBC cell lines." (PMID 35897832, 2022). "Implicit in the disconnection between the two observations (treatment of BV-2 microglial cells with ΔANXA1 4T1 CM versus 4T1 CM with FPRs antagonists) is the interpretation that FPR1/2 was still activated despite genomic deletion of ANXA1 in 4T1 metastatic mammary cancer cells." (PMID 35382852, 2022).
breast carcinoma (continued). "An attempt to illustrate the role of ANXA1-FPRs axis in the crosstalk of metastatic mammary cancer cells and microglial cells, revealed that STAT3 as the downstream mediator of this interaction, working antagonistically to the ERK-STAT1 axis induced by 4T1 CM in BV-2 microglia." (PMID 35382852, 2022). "High AnxA1 expression levels have been found in breast cancer, melanomas, hepatocellular carcinomas, colorectal cancers, gliomas, lung adenocarcinomas and prostate cancer, correlating with worse prognosis, lower disease-free survival rates and lower overall survival." (PMID 34571894, 2021). "Furthermore, overexpression of ANXA1 was reported to increase resistance to chemoradiotherapy in colorectal and breast cancer." (PMID 34200100, 2021). "Reported roles of Annexin A1 in breast cancer progression and metastasis are contradictory." (PMID 33800279, 2021). "Interestingly, lower ANXA1 levels were negatively correlated in ER + MCF-7 breast cancer cells with higher expression levels of oncogenic miR-196a and repression of c-myc and NFκβ." (PMID 34207035, 2021). "The authors concluded that the AnxA1 signaling regulates the function of Tregs; hence, this could be an ideal target for innovative therapies against breast cancer." (PMID 34571894, 2021). "Adding further complexity, secretion of AnxA1 from TNBC cells might induce autocrine signalling via FPR1 to further increase breast cancer cell aggressiveness and survival and could be blocked with cyclosporin A, a FPR1 inhibitor." (PMID 33810523, 2021). "In Hannah L’s study, ANXA1 was able to protect against DNA damage and promote modulation of cell adhesion and motility, indicating its potential role in cancer initiation and progression in breast carcinoma." (PMID 34484309, 2021). "Further research is required to uncover the relevant features of human breast cancers that might render them vulnerable to inhibition of Annexin A1 function(s)." (PMID 33800279, 2021). "miR-196a-5p has shown to inhibit ANXA1 and enhance breast cancer cell growth." (PMID 33790326, 2021). "Conversely, stable Annexin A1 knockdown in EpRas mouse mammary cancer cells, driven by an activated Ras oncogene, indicated that endogenous Annexin A1 promoted the epithelial phenotype and also abrogated both orthotopic mammary tumor growth and spontaneous metastasis to lung." (PMID 33800279, 2021). "Interestingly, PPARγ has also been shown to increase ANXA1 expression by binding to the promoter of ANXA1 in breast cancer cells." (PMID 32894039, 2020). "In breast cancer, both tumour suppressor and oncogenic activity have been attributed to ANXA1." (PMID 33276477, 2020). "ANXA1 is known to constitutively activate NF-κB in breast cancer cells by interacting with the IKK complex, an interaction that might not to be relevant in μg." (PMID 31731625, 2019). "However, the relationship between ANXA1 levels and patient survival in breast cancer has been inconsistent in prior studies." (PMID 31461932, 2019). "ANXA1 expression is low in breast cancer and negative expression is associated with the homozygous CC genotype and the C/T variant of miR-196a rs11614913." (PMID 31777500, 2019). "Throughout the years of investigation Annexin A1 (AnxA1), Annexin A2 (AnxA2), Annexin A3 (AnxA3), Annexin A4 (AnxA4), Annexin A5 (AnxA5), Annexin A6 (AnxA6), and Annexin A8 (AnxA8) have all been identified as potential modulators of breast cancer progression." (PMID 29416802, 2018). "AnxA1, AnxA2, and AnxA6 were the only annexins identified to be significantly associated with clinical outcomes of TNBC patients in comparison with all other breast cancer subtypes." (PMID 29416802, 2018). "AnxA1 also positively regulates TGF-β signalling in breast cancer cells." (PMID 29449195, 2018).
breast carcinoma (continued). "Taken together, these data suggest that macrophage ANXA1 plays an important role in the tumour microenvironment which can promote breast cancer growth and migration, possibly through the induction of macrophage polarization to an alternatively activated immunosuppressive phenotype (M2)." (PMID 29263330, 2017). "Hence, here we extend our previous work by investigating the phosphorylation landscape in ANXA1+/- and ANXA1-/- murine mammary gland cells to understand the ANXA1-modulated signaling network upon breast cancer initiation." (PMID 29233185, 2017). "Though ANXA1 levels correlate with breast cancer disease status and outcome, its distinct functional involvement in breast cancer initiation and progression remains unclear." (PMID 29233185, 2017). "Furthermore, HIDEEP reveals that doxorubicin directly targets TOP2A, one of breast cancer-causing genes, and dexamethasone has impacts on TOP2A through HEPs such as ANXA1 → SUMO3 → TOP2A and NR0B1 → UBC → TOP2A." (PMID 29192270, 2017). "The phosphoproteome landscape uncovered several novel perspectives for ANXA1 in mammary gland biology and highlighted its involvement in key signaling pathways modulating cell adhesion and migration that could contribute to breast cancer initiation." (PMID 29233185, 2017). "All these data suggest that inhibiting onco-miR-196a expression may be one of the possible mechanisms by which ANXA1 suppresses cell growth in breast cancer cells, and on the other hand, miR-196a may induce breast cancer cell proliferation by targeting ANXA1." (PMID 27105503, 2016). "We have previously reported that ANXA1 reduced miRNA expression in breast cancer cells, but the mechanism was unknown." (PMID 27105503, 2016). "This indicates that the miR-196a directly targets ANXA1 in breast cancer cells." (PMID 27105503, 2016). "ANXA1 inhibits the biogenesis of oncogenic miR-196a by suppressing primary-miR196a indirectly through the stimulation of c-myc and NFkB expression and activity in breast cancer cells." (PMID 27105503, 2016). "Importantly, our study is the first to report that ANXA1 and miR-196a form a regulatory loop to modulate breast cancer cell proliferation." (PMID 27105503, 2016). "In addition, Annexin-A1 increases breast cancer invasion by activating RhoA in an ERK-dependent fashion." (PMID 27391444, 2016). "Although ANXA1 has been described to play a role in metastasis formation in breast cancer, the exact mechanism remains unknown." (PMID 26137966, 2015). "ANXA1 expression was higher in the tumors from BRCA1/2 mutated patients compared to BCAC patients overall: 48.6 % versus 12.4 %, respectively; P <0.0001, and within specific breast cancer subtypes." (PMID 26137966, 2015). "We hypothesized that the annexin A1 plays an oncogenic role in basal subtype of breast cancer by modulating key growth pathway(s)." (PMID 26000884, 2015). "The association between ANXA1 expression and basal markers (EGFR-CK5/6) as shown in this study was also described in our previous work using a smaller cohort of breast cancer patients, suggesting that ANXA1 may play a role in EGFR trafficking." (PMID 26137966, 2015). "There are conflicting reports in the literature about the role annexin A1 plays in breast cancer." (PMID 26000884, 2015). "The BRCA1/2 mutated patients belong to a group that already contains a high number of triple negative and basal-like breast cancers, but here we showed that triple negative tumors in BRCA1/2 mutated carriers are even more highly expressing ANXA1 than triple negative patients in the BCAC cohort." (PMID 26137966, 2015). "Our data suggest that annexin A1 is prognostic only in patients with basal like breast cancer." (PMID 26000884, 2015). "Consistent with this laboratory based findings; annexin A1 mRNA levels were significantly higher in basal-like breast cancer patients (n = 139) than in samples from patients with luminal (n = 685) or Her2/neu+ positive (n = 66) cancers (TCGA breast cancer dataset)." (PMID 26000884, 2015).
breast carcinoma (continued). "However, contradictory descriptions on ANXA1 expression were reported in certain human tumors, e.g., breast cancer, bladder cancer, and gastric cancer as well." (PMID 25038797, 2014). "However, more recently, ANXA1 protein has been recognized to be differentially expressed in various human tumors, e.g., breast cancer, prostate cancer, esophageal cancer, gastric cancer, endometrial carcinoma, pancreatic cancer, and colorectal cancer." (PMID 25038797, 2014). "As ANXA1 constitutively activates NF-κB activity to modulate breast cancer metastasis, we found that miR26b* and miR562 directly targeted the canonical NF-κB pathway by targeting the 3′ UTR and inhibiting expression of Rel A (p65) and NF-κB1 (p105) respectively." (PMID 25536365, 2014). "However, increased Annexin A1 expression has also been reported in breast cancer, bladder cancer, pancreatic cancer, liver cancer, esophageal cancer, lung cancer." (PMID 23786757, 2013). "In contrast, Annexin A1 overexpression in breast cancer correlates with a better survival." (PMID 23786757, 2013). "Moreover, it has been recently proposed that ANXA1 enhances breast cancer invasion, at least in part, through the activation of NF-kappaB and the expression of the matrix metalloproteinase -9 gene." (PMID 24023790, 2013). "Furthermore, the immunological landscape of breast cancer is complex and influenced by numerous factors beyond ANXA1 and MHC‐II expression, such as the presence of other immune checkpoints, the diversity of the tumor microenvironment, and individual patient variability." (PMID 40744683, 2025). "It is not possible to speculate whether ECM1 and ANXA1 in the uEVs are associated with the survival and cure rate of breast cancer." (PMID 39040439, 2024). "Furthermore, ROC curve analysis demonstrated that the protein levels of ECM1 and ANXA1 in uEVs could effectively differentiate between breast cancer patients and healthy controls or patients with benign breast nodules." (PMID 39040439, 2024). "Thus, we speculated that overexpression of NTF4 would induce breast cancer cell apoptosis by ANXA1 nuclear translocation." (PMID 36632451, 2023). "Hence, NTF4 or NTF4 combined with ANXA1 may be biomarkers for breast cancer prognosis, especially for early stage breast cancer patients at risk for metastasis." (PMID 36632451, 2023). "Another protein ANXA1 (downregulated in MC7 and BT20 E2 treated and WWOX-depleted cells) which was previously reported to regulate EMT and is associated with highly invasive basal-like breast cancer phenotype was found also to contribute to trastuzumab resistance through AKT activation." (PMID 35290621, 2022). "Moreover, ANXA1 contributes to the ERK-NFκB activation loop in breast cancer cells." (PMID 35974388, 2022). "Additionally, another study examined ANXA1 in breast cancer found that ANXA1, could bind to NEMO at a high level, thereby stabilizing the IKK complex and ultimately inducing the activity of NF-κB." (PMID 36386180, 2022). "However, one study found lower Annexin A1 protein expression in metastatic primary human breast cancers compared to non-metastatic and an association between Annexin A1 expression and better metastasis-free and overall patient survival." (PMID 33800279, 2021). "Collectively, our data demonstrate a novel cell-autonomous role for Annexin A1 in the promotion of tumor-forming capacity in a model of human breast cancer and suggest that some basal-like TNBCs may require high endogenous tumor cell Annexin A1 expression for continued growth." (PMID 33800279, 2021). "Other limitations to boost anticancer immunity in cancer patients via AnxA1 administration include the high prevalence of a loss-of-function FPR1 allele common in all ethnic groups, which is associated with poor prognosis, at least in breast cancer patients, after anthracycline-based chemotherapy." (PMID 33810523, 2021).
breast carcinoma (continued). "It was reported to be elevated in hepatocellular carcinoma, breast cancer, gastric cancer and melanoma, while decreased in nasopharyngeal carcinoma, prostate cancer and esophageal carcinoma, indicating the context-dependent role for ANXA1 in carcinogenesis 10-15." (PMID 33531975, 2021). "Studies in breast cancer have found that in the absence of detectable levels of P-glycoprotein and the breast cancer resistance protein, ANXA1 upregulation is associated with increased resistance to several anticancer drugs, including doxorubicin, melphalan, and etoposide." (PMID 32226772, 2020). "Many of these are enzymes or cytoskeletal proteins (ANXA1, KRT10, KRT16, TUBB, ACTB, ACTA1, PKM2, and HSPA8) that have been previously reported as able to induce autoantibodies with diagnostic potential across different tumor types, including PDAC, breast cancer, and neuroblastoma." (PMID 30651550, 2019). "Thus, ANXA1 may be predictive of trastuzumab resistance in patients with HER2-positive breast cancer." (PMID 29416786, 2018). "However, in breast cancer cells, cytoplasmic ANXA1 can activate NF-κB either directly by interacting with and stabilizing the NEMO-RIPI-IKK complex or indirectly by inhibiting miR-26b and miR-562, which directly silence the NF-κB pathway by recognizing p65 and p105 mRNAs at the 3′-UTR." (PMID 29662435, 2018). "We have previously demonstrated that ANXA1 can associate with NF-κB and increase c-Myc activity leading to the inhibition of miR196a transcription, inducing a negative feedback loop to promote breast cancer migration and metastasis." (PMID 29263330, 2017). "Finally, to analyse the potential impact of tumor microenvironment derived ANXA1 on the regulation of tumour growth in vivo, 4T1 murine breast cancer cells which harbor a luciferase promoter (4T1-12B) were injected into the 4th left mammary gland of female BALB/c WT and ANXA1−/− mice." (PMID 29263330, 2017). "The exact role of annexin A1 in the biology of breast cancer remains unclear." (PMID 26000884, 2015). "Thus, in this study, we hypothesize that annexin A1 plays an oncogenic role in basal like breast cancer." (PMID 26000884, 2015). "However, little is known about the prognostic value of ANXA1 in breast cancer." (PMID 26137966, 2015). "Therefore, we investigated the regulation of miR by ANXA1 in MCF7 breast cancer cells." (PMID 25536365, 2014). "Thus, ANXA1 can be established as playing a dualistic role in breast cancer progression." (PMID 25536365, 2014). "In addition, recent studies have shown that Annexin1 (ANXA1), which was listed as a gene downregulated by BRG1 knockdown, regulates TGF-β signalling and promotes metastasis formation; loss of ANXA1 was associated with tumour progression in human breast cancer." (PMID 21102582, 2011). "The uEVs were found to contain ECM1 and ANXA1, which were validated by CLIA as effective markers for discriminating breast cancer patients from healthy controls or patients with benign breast nodules." (PMID 39040439, 2024). "Secondly, NTF4 is a new regulator of breast cancer EMT and cancer progression, which targets PRKDC (DNA-PKcs) and ANXA1 and activate AKT and NF-κB pathways." (PMID 36632451, 2023). "Western blots demonstrated knock-down of ANXA1 to inhibit the NF-κB pathway and the expression of mesenchymal markers (N-cadherin and SNAIL) as well as breast cancer cell migration and invasion." (PMID 36632451, 2023). "High levels of ANXA1 have been found in CRC, breast cancer, and melanoma, correlating with poor prognosis, low disease-free survival, and low overall survival." (PMID 37986009, 2023). "All in all, our work provides mechanistic insights into how microglia, in the brain tumor microenvironment, respond to metastatic breast cancer cells through activation of FPR1/2-STAT3 axis, driven by ANXA1 paracrine/autocrine loop." (PMID 35382852, 2022).